GRIK4 (glutamate ionotropic receptor kainate type subunit 4)
Description:
Ionotropic glutamate receptor that functions as a cation-permeable ligand-gated ion channel. Cannot form functional channels on its own. Shows channel activity only in heteromeric assembly with GRIK1, GRIK2 and GRIK3 subunits (By similarity).
Synonyms: GluK4; EAA1; KA1; GRIK; GluK4-2
Tractability: Small molecule: an approved drug acts on it; it belongs to a druggable protein family. Antibody: UniProt places it where antibodies can reach, with high confidence; its Gene Ontology location is reachable by antibodies, with high confidence; UniProt predicts a signal peptide or a membrane-spanning region. PROTAC: a small molecule that binds it is known.
Gene: Protein-coding gene on chromosome 11 (120,511,717 to 120,988,906, forward strand). Ensembl gene ENSG00000149403.
Subcellular location: Cell membrane; Postsynaptic cell membrane; Presynaptic cell membrane
Pathways (Reactome):
Neuronal System: Activation of Ca-permeable Kainate Receptor
Gene Ontology:
Molecular function: ligand-gated monoatomic ion channel activity involved in regulation of presynaptic membrane potential; kainate selective glutamate receptor activity; transmitter-gated monoatomic ion channel activity involved in regulation of postsynaptic membrane potential; ligand-gated monoatomic ion channel activity; monoatomic ion channel activity; signaling receptor activity
Biological process: chemical synaptic transmission; glutamate receptor signaling pathway; modulation of chemical synaptic transmission; synaptic transmission, glutamatergic; ionotropic glutamate receptor signaling pathway; monoatomic ion transmembrane transport; monoatomic ion transport; regulation of postsynaptic membrane potential; regulation of presynaptic membrane potential; signal transduction
Cellular component: glutamatergic synapse; kainate selective glutamate receptor complex; plasma membrane; postsynaptic density membrane; postsynaptic membrane; presynaptic membrane; hippocampal mossy fiber to CA3 synapse; membrane; synapse
Genetic constraint (gnomAD): Loss-of-function variants: 31 observed, 71.3 expected, observed/expected ratio (o/e) 0.43, 90% interval 0.33 to 0.59. The upper end of that interval is the gene's LOEUF score, 0.59, which puts it in group 2 of 6, group 1 being the genes least tolerant of losing a copy. Missense variants: 871 observed, 1,048.2 expected, observed/expected ratio (o/e) 0.83, 90% interval 0.79 to 0.88. Synonymous variants: 410 observed, 429.48 expected, observed/expected ratio (o/e) 0.95, 90% interval 0.88 to 1.04.
Homologues: Orthologues: macaque GRIK4 (99% identical), guinea pig GRIK4 (99% identical), pig GRIK4 (99% identical), rabbit GRIK4 (99% identical), mouse Grik4 (98% identical), rat Grik4 (98% identical), chimpanzee GRIK4 (98% identical), tropical clawed frog grik4 (87% identical), dog GRIK4 (86% identical), zebrafish grik4 (80% identical), Drosophila melanogaster CG11155 (36% identical), Drosophila melanogaster Ekar (32% identical), and 37 more. Paralogues in human: GRIK5 (69% identical), GRIK2 (41% identical), GRIK1 (39% identical), GRIK3 (39% identical), GRIA3 (32% identical), GRIA1 (32% identical), GRIA4 (32% identical), GRIA2 (32% identical), GRID1 (25% identical), GRID2 (25% identical), GRIN1 (23% identical), GRIN2B (19% identical), and 5 more.
Diseases named in the same sentence as GRIK4 in open-access papers:
GRIK4 is named in the same sentence as 36 diseases in open-access papers, as found by Europe PMC text mining. Sharing a sentence is not in itself a finding about the gene and the disease. The quoted sentences say what the papers report.
schizophrenia (13 papers, 2012 to 2025). A major psychotic disorder characterized by abnormalities in the perception or expression of reality. "Among the genes with two hits uniquely in cases were three candidate genes linked to autism by a literature-curated database, DMD, SYNE1, and TBL1X and two genes implicated in schizophrenia (GRIK4) and intellectual disability (PQBP1)." (PMID 26185613, 2015). "After resequencing 516 unrelated patients with schizophrenia, 44 protein-altering variants were identified, including 12 in the GRIK1, 5 in the GRIK2, 7 in the GRIK3, 13 in the GRIK4, and 7 in the GRIK5." (PMID 35629206, 2022). "The GRIK gene family (GRIK1, GRIK2, GRIK3, GRIK4, and GRIK5) has genetic variants that contribute to various illnesses, including Huntington's disease, Parkinson's disease, autism, and schizophrenia." (PMID 41327126, 2025). "Therefore, we sequenced the exonic regions of five kainate receptor genes (GRIK1, GRIK2, GRIK3, GRIK4, and GRIK5) to identify rare pathogenic variants in patients with schizophrenia using the ion semiconductor sequencing method." (PMID 35629206, 2022).
depression (9 papers, 2009 to 2025). "Another study reported that glutamate ionotropic receptor kainate type subunit 4 variants were involved in treatment-resistant depression." (PMID 31281445, 2019). "The GRIK gene family (GRIK1, GRIK2, GRIK3, GRIK4, and GRIK5) has genetic variants associated with many psychiatric illnesses including; depression, obsessive–compulsive disorder, and autism." (PMID 41327126, 2025). "Of thirteen depression‐associated DRPs, seven proteins including DDC, FGFR2, KIBRA, MED22, OLIG1, RAI1, SLIT2 were upregulated, whereas six proteins including COX3, CRHBP, CSMD1, FSTL1, GRIK4, and LMTK3 were downregulated." (PMID 39373701, 2024). "Although there is a lack of previous research on rs7105363, polymorphisms in GRIK4 have been associated with treatments for depression and bipolar disorder." (PMID 39194753, 2024). "By contrast, the upregulation of DDC, FGFR2, KIBRA, and MED22, and the downregulation of FSTL1, GRIK4, and LMTK3 in the RagA transgenic mice were negatively correlated with depression." (PMID 39373701, 2024). "GRIK4 and PDE9A contribute to critical pathways involved in depression and antidepressant response, including glutamatergic signalling, neuroplasticity and neurogenesis." (PMID 33589590, 2021).
bipolar disorder (7 papers, 2015 to 2024). A disorder of the brain that causes unusual shifts in mood, energy, activity levels and the ability to carry out day-to-day tasks. "Interestingly, a deletion variant specific to the 3′ UTR of GRIK4 is protective of bipolar disorder." (PMID 29244006, 2017). "GRIK4 regulates kainite-receptor signaling and neuroplasticity and its missregulation is associated with neurological diseases including Alzheimer’s, bipolar disorder, and others." (PMID 29244006, 2017). "For instance, we excluded an indel within the 3′UTR of GRIK4 which we previously reported confers protection against developing bipolar disorder through altering GluK4 RNA and protein abundance." (PMID 31844109, 2019).
Anxiety (6 papers, 2016 to 2025). Intense feelings of nervousness, tension, or panic often arise in response to interpersonal stresses. "Additionally, overexpression of GRIK4, a gene encoding KA1, induced an altered synaptic transmission in mice that also manifested ASD-associated symptoms such as enhanced anxiety, depressive states, and impaired social interactions." (PMID 28331639, 2017). "Mice with forebrain GluK4 overexpression exhibit altered synaptic transmission and display several autistic-like behaviors including social impairment, enhanced anxiety, and depressive states, coinciding with the finding of GRIK4 duplications in individuals with ASD." (PMID 27909399, 2016).
epilepsy (2 papers, 2016 to 2020). A brain disorder characterized by episodes of abnormally increased neuronal discharge resulting in transient episodes of sensory or motor neurological dysfunction, or psychic dysfunction. "In order for us to be able to investigate the possible role of the SV2A protein in epilepsy, we first studied a conditional mouse line carrying SV2A deletion in the hippocampus (i. e., Grik4:SV2A-cKO)." (PMID 27861538, 2016). "The possibility thus exists that GriK4:SV2A-cKO does not affect the neuronal population responsible for epilepsy, as the GABAergic system is preserved." (PMID 27861538, 2016). "Additionally, the mediumblue module (Pvalb subtypes, 173 genes), while not passing the test for associating more strongly with epilepsy than with any sample, included the genes GRIK1, GRIK2, GRIK4, GRM1, GRM7, and GRIA1, suggesting a potential involvement in glutamate receptor subunits." (PMID 33028830, 2020).
glioblastoma (2 papers, 2021 to 2024). The most malignant astrocytic tumor (WHO grade IV). "To sum up, we identified seven genes (GRIA1, GRIA2, GRIK1, GRIK4, GRM3, GLUL, BCAT1) whose mRNA expression may serve as potential molecular biomarker candidates to distinguish glioblastoma and brain metastases tissue derived from surgical resections." (PMID 38835368, 2024).
anxiety disorder (1 paper, 2023). A category of psychiatric disorders which are characterized by anxious feelings or fear often accompanied by physical symptoms associated with anxiety. "Various other genes have been implicated in the efficacy of CBT/iCBT in treating anxiety disorders, such as Glutamate Receptor, Ionotropic Kainate 4 (GRIK4), Hypocretin/hypocretin receptor 1 (HCRTR1), and Interleukin 1 Receptor Type 1 (IL1R1)." (PMID 37497400, 2023).
bone cancer (1 paper, 2013). A primary or metastatic malignant neoplasm affecting the bone or articular cartilage. "Although glutamate signaling in primary bone cancers is not well understood, both GRM4 and GRIK4 are expressed in normal bone, and glutamate signaling has been shown to regulate bone formation and resorption." (PMID 24330828, 2013).
colitis (1 paper, 2024). Inflammation of the colon. "Additionally, spatial transcriptome analysis also found that other receptors such as NMDAR2C/D, NMDAR3A, and AMPA receptor GRIK4/5 were highly increased in the hippocampus of DSS‐induced colitis mice." (PMID 38676295, 2024).
glaucoma (1 paper, 2021). Increased pressure in the eyeball due to obstruction of the outflow of aqueous humor. "These 13 glaucoma-associated genes can be divided into three functional groups: phototransduction-related genes (GNGT1, OPN1SW, PDE6A, PDC, CRX, CNGB1, GUCY2F), glutamate receptor (GR) genes (GRIN2B, GRIK3, GRIK4), and 5-hydroxytryptamine receptor (HTR) genes (HTR1A, HTR1E, HTR7)." (PMID 33874942, 2021).
ischemia (1 paper, 2025). A hypoperfusion of the BLOOD through an organ or tissue caused by a PATHOLOGIC CONSTRICTION or obstruction of its BLOOD VESSELS, or an absence of BLOOD CIRCULATION. "Namely, the peptide reduced the expression of many genes (e.g., P2rx6, Gabra3, Grik4, Oprl1, Glra2, Crhr1, Hrh1, Chrm5, Grik1) related to the neurosignaling system and whose expression was not significantly changed by ischemia itself." (PMID 40650034, 2025).
retinal degeneration (1 paper, 2022). Degeneration of the retina. "The Grik4 construct is known to restrict expression to a well-defined population of direction-sensitive RGCs28 and L7 mainly to retinal ON bipolar cells in mice (such as the widely used rd1 model of retinal degeneration employed here)." (PMID 35402632, 2022).
psychiatric disorder (3 papers, 2009 to 2025). A disorder characterized by behavioral and/or psychological abnormalities, often accompanied by physical symptoms. "GRIK4 encodes a kainate receptor subunit involved in glutamatergic synaptic transmission, and its dysregulation is linked to major psychiatric disorders." (PMID 40640508, 2025).
tumor (3 papers, 2017 to 2025). "Our findings suggest that resistance-associated DEGs such as RAMP1, GSG1L, and GRIK4 may contribute to shaping the tumor microenvironment through interactions with M0/M2 macrophages and resting CD4+ memory T cells." (PMID 41234433, 2025). "In contrast to tumors, the adjacent non-tumor tissues harbored eight genes with recurrent HBV integration, including FN1, DCC, OAZ2, ANO3, ENOX1, GRIK4, NPAT, and SNCAIP." (PMID 34209079, 2021).
movement disorder (1 paper, 2022). Neurological conditions resulting in abnormal voluntary or involuntary movement, which may impact the speed, fluency, quality and ease of movement. "The GRIK4 kainate receptor was strongly associated with excitotoxic neurodegeneration (in the hippocampus), but nothing is known about its relation to movement disorders." (PMID 35885427, 2022).
GRIK4 also shares sentences with these, for which no sentence is quoted: autism (5 papers); Intellectual disability (3); glioma (2); infection (2); psychosis (2); Alzheimer disease (1); amyotrophic lateral sclerosis (1); astrocytomas (1); autism spectrum disorder (1); cancer (1); cognitive deficits (1); episodic ataxia type 6 (1); Huntington disease (1); lung adenocarcinoma (1); mental disorder (1); neurodegenerative disease (1); neurological diseases (1); Parkinson disease (1); small cell lung carcinoma (1); tendinopathy (1); type II diabetes (1).